IL5 (interleukin 5)
Diseases named in the same sentence as IL5 in open-access papers (continued):
Sharing a sentence is not in itself a finding about the gene and the disease.
infection (continued). "Shortly after the beginning of egg deposition, a strong egg-specific Th2 response develops characterized by high levels of IL-4, IL-5, and IL-13 which decreases when the infection enters the chronic stage." (PMID 20537152, 2010). "Transcript levels for various cytokines/chemokines (KC [CXCL1], MCP-1 [CCL2], MIP-1α, IFN-γ, IL-4, IL-5, IL-6 and IL-10) were determined in lungs of infected mice on days 1, 6 and 9 post-infection." (PMID 20661429, 2010). "In egg-negative people IL-10 levels followed the age-infection profile while IL-5 levels lagged behind, only beginning to rise when infection levels peaked." (PMID 21039611, 2010). "In comparison to C57Bl/6 mice, Balb/c had delayed IFN-γ and IL-6 response, an early IL-10 that persisted to day 15 and increased by day 28 post-infection, and IL-5 levels that were significantly elevated by day 15 and remained so at day 28 post-infection." (PMID 20625554, 2010). "By contrast, the production of helminth-specific Th2 cytokines, such as IL-4 and IL-5, was suppressed by infection with T. gondii." (PMID 19478853, 2009). "IL-5 levels in moribund animals were significantly lower than in animals on day 11 post infection (p < 0.001, Bonferroni corrected)." (PMID 19250545, 2009). "For example, infection with F. hepatica induces potent Th2 responses, characterised by production of IL-4, IL-5 and IL-10." (PMID 19478853, 2009). "IL-2, IL-4, IL-5 levels on day 4 were significantly lower than the levels in moribund animals or in animals on day 11 post-infection (p < 0.001, Bonferroni corrected)." (PMID 19250545, 2009). "WT mice displayed significant increases in Retnla, Il4, Il5, Il13, and Ccl11 (Eotaxin) mRNA expression following infection with N. brasiliensis, while Il25 and the mucin genes Muc5ac and Gob5 were not altered." (PMID 19381262, 2009). "As IgE and eosinophils are highly dependent on IL-4, Il-5 and IL-13, it was thought that protection against infection by Schistosoma would involve a Th2 immune response." (PMID 19471606, 2008). "Infection levels are mainly regulated by a major locus SM1, in 5q31-q33 region, which contains the genes encoding for the IL-4, IL-13, and Il-5 cytokines." (PMID 19471606, 2008). "Levels of IL-10 rose to peak with infection intensity in 11–12 year olds, while levels of IL-4 and IL-5 rose more slowly peaking later in 15–16 year olds." (PMID 18045464, 2007). "IL-5 was expressed at both time points (4 h and 1 d pi), showing a decreasing level of expression with ongoing infection." (PMID 17524146, 2007). "People carrying high levels of infection (>50 eggs/10 ml urine) tended to make low levels of IL-5 (<10 ng/ml), while people with higher IL-5 levels had low levels of infection although this relationship was not statistically significant." (PMID 18045464, 2007). "However, the infection predominantly induces a Th2‐biased immune profile, characterized by elevated levels of IL‐4, IL‐5, IL‐10, IL‐23, and IL‐13, which appears to support parasite survival within the host." (PMID 41503693, 2026). "We expected to see classic rise-fall kinetics in the concentrations of CCL11 and IL-5 for the breakthrough infection mice, corresponding with the gradual influx of lung eosinophil counts, but the kinetics for these two analytes did not appear clearly linked to eosinophil numbers." (PMID 41190814, 2025). "Cytokine levels decreased for 6 of 9 assayed cytokines or the chemokine in the Chr7x3 AAB variant (IL-17a, IL-22, IL-5, IFN-γ, TNF-α, and IL-1β) and further decreased for all cytokines and the CXCL1 chemokine in the Chr7x3 ABB variant when compared to infection with Chr7x2 SC5314." (PMID 40577316, 2025). "Cytokine levels decreased for 6 of 9 assayed cytokines or the chemokine in the Chr7×3 AAB variant (IL-17a, IL-22, IL-5, IFN-γ, TNF-α, and IL-1β) and further decreased for all cytokines and the CXCL1 chemokine in the Chr7×3 ABB variant when compared to infection with Chr7×2 SC5314." (PMID 39896449, 2025).
infection (continued). "It seems that the infection had the biggest impact on IL-5 production." (PMID 40918106, 2025). "Similarly, CD131, which is shared by GM-CSF, IL-3, and IL-5 signaling, was expressed in most developmental stages and was markedly enhanced upon infection." (PMID 39868131, 2025). "In the relatively susceptible BALB/c strain, infection of mice lacking of eosinophils (IL-5 knockout or ΔdblGata1 mice) increases parasite survival and filarial embryogenesis compared to wild-type mice." (PMID 40644522, 2025). "Additionally, Type 2 cytokines such as IL-4 and IL-13 were also present in the primary infection mice at these two time points, and with significantly higher IL-5 expression at 7 DPC than all other groups." (PMID 41190814, 2025). "Heterologous infection of wild-type mice significantly increased mRNA expression of Il4, Il5, Il13." (PMID 41573550, 2025). "IL-13 and IL-5 genes were strongly up-regulated in animals with previous exposure to the infection." (PMID 38338687, 2024). "A factor analysis study in Zimbabwean children similarly found that a composite variable representing IL-5, IL-10, and IFN-γ increased with age and was positively associated with current Sh infection as well as with past Sh exposure determined by the presence of Sh-specific antibodies in serum." (PMID 39250522, 2024). "However, long-term infection drives the immune system towards a Th2 response with high levels of IL-4, IL-5, IL-13, and immunosuppressive IL-10 and TGF-β, leading to tolerance." (PMID 38817444, 2024). "Thus, CD4+ T cell-secreted IL-4 and IL-5 can enhance both the primary B cell responses to vaccination and future responses to infection or vaccination." (PMID 38543915, 2024). "In G6, IL-2, IL-12, IL-4, and IL-5, involved in the growth, proliferation, and differentiation of Th1 and Th2 cells, were notably less expressed in the early days post-infection compared to G1a, where an expression level comparable to or higher than the controls was observed." (PMID 38891666, 2024). "However, the actual expression of IL-4 and IL-5 proteins returned to the levels in naïve Th2 cells at 40 days post-infection and further decreased at 60 days post-infection." (PMID 38788198, 2024). "Furthermore, it resulted in decreased levels of Th2 cytokines (IL-4, IL-5, and IL-13) after infection, while interferon γ levels remained largely unchanged." (PMID 38016013, 2024). "As the infection progresses, a delicate shift occurs, characterized by a transition to adaptive immunity, guided by cytokines like interleukin-4 (IL-4), interleukin-5 (IL-5), and interleukin-13 (IL-13), promoting antibody production and T-cell responses." (PMID 38694310, 2024). "Specifically, there was an increase in the levels of the cytokine IL-5 and IL-13 in relation to the number of exposures to infection, as well as an increase in these cytokines related to the increase in the dose of infection." (PMID 39621794, 2024). "Notably, IL-5 and IL-4 levels were also reduced in these mice, suggesting enhanced resistance to infection." (PMID 39635124, 2024). "In addition, Th2 cytokines including IL-4 and IL-5 were also decreased in Ifngr1-/- mice following infection, suggesting the downregulation of both type 1 and 2 immune responses in the absence of IFN-γ signaling." (PMID 38743761, 2024). "The infection with Mtb increased the production of IL-10, IL-13, and IL-5." (PMID 37375056, 2023). "To determine whether early sources of IL-5 perturb host responses to F. tularensis LVS infection, we treated mice before and during infection with an anti–IL-5 Ab and measured bacterial burdens." (PMID 36602520, 2023). "After infection, animals generate IL-4, IL-5, and IL-10, resulting in a Th2 response." (PMID 37110723, 2023). "Additionally, there was a significant decrease production of 13.8-fold in IL-4, 21.3-fold in IL-5, and 12.6-fold in IL-13 at day 90, compared to the highest levels observed at 30 days of infection." (PMID 37691941, 2023).
infection (continued). "Moreover, after infection for 8–10 days, the nILC2s in the lung were significantly increased, with high expression of IL-13 and IL-5, as well as a small amount of IL-4." (PMID 37173731, 2023). "This dynamic study of F. gigantica-infected buffalo serum cytokines has revealed that, in the early stages of both primary and secondary infection, Th2/Treg dominated response was induced; this was manifested in increases of IL-4, IL-5, IL-10, IL-13, and TGF-β and reduction of IFN-γ and IL-17." (PMID 37152685, 2023). "The infection of bacteria or viruses can trigger type I pro-inflammatory immune responses (e.g., IFN-γ, TNF-α, TH1 cells), whereas infection by helminths typically elicits a type II host resistance and tolerizing immune response (e.g., IL-4, IL-5, IL-13, TH2 cells)." (PMID 37789420, 2023). "Interestingly, IL-5 overexpression accelerated larval growth during the early infection, suggesting that eosinophil-mediated protection increases developmental pressure on the larvae." (PMID 36389745, 2022). "This would imply that IL-5 might be a strategy used by EPEC to dampen inflammation during early infection." (PMID 35924851, 2022). "IL-5 is a type 2 cytokine functioning as an immunomodulator, upregulation of which might compromise the early immune defense against infection." (PMID 35672716, 2022). "However, little is known about IL-5, IL-33 and type 2 alveolar epithelial cells in the course of C. gattii experimental infection." (PMID 36145419, 2022). "For instance, increased periodontal pathogen abundance will enhance the stimulation of TLRs, induce Th1 to secrete IL-2, IFN-γ, TNF-α to kill intracellular infection pathogens, and then induce Th2 to secrete IL-4, IL-5, IL-6, IL-13 to regulate humoral immunity and limit Th1 response." (PMID 35254118, 2022). "This hypothesis could explain IL-5, IL-1, IL-6, and IL-18 increased expression in the spleen after 2 weeks of infection following the upregulation in the intestine." (PMID 36187827, 2022). "IL-5 has been shown to play a crucial role in the immune response to challenge infection." (PMID 36405584, 2022). "Stimulation of eosinophils by addition of IL-5 before infection in mice lacking TCD4 or completely deficient in lymphocytes leads to a better clearance of the fungus at 14 days post-infection, without any increase in the Th2 response." (PMID 34436164, 2021). "As expected, ΔILC2 mice showed evidence of increased ILC2 activity as reflected by IL-13 expression by lung ILC2s and by IL-5 expression in whole lung tissue at the peak of infection (day 7), as well as by ILC2 expansion during the resolution phase (day 14), as compared to WT mice." (PMID 34290377, 2021). "VIP can bind to VIP receptor 2 (VPAC2) on the surface of ILC2s, thus promoting ILC2s to secrete IL-5, which can recruit eosinophils, participate in infection and immune response, and sensory neurons can secrete vasoactive intestinal peptide under IL-5 stimulation." (PMID 34659628, 2021). "On the contrary, post–lung-stage infection increased IL-4 and IL-5 secretion." (PMID 34169075, 2021). "However, this impairment was not sustained during the course of infection as it disappeared at subsequent infection time points (U = 6, P = 0.6857; U = 1, P = 0.4 for IL-5 and U = 3, P = 0.2; U = 1, P = 0.4 for IL-13 at 9 and 12 wpi, respectively)." (PMID 33482904, 2021). "However, they either significantly subsided (IL-4 and IL-5) or maintained at a similar level (IL-13) in immunized mice in response to an infection with CO92." (PMID 33514747, 2021). "Type-I T cells produced type-I cytokines, such as IL-2, TNF-α, and IFN-γ, to enhance cellular response to remove infected cells, whereas Type-II T cells produced type II cytokines, such as IL-4, IL-5, and IL-10, to increase antibodies to attack exogenous antigen to prevent host-cell infection." (PMID 34200327, 2021).
infection (continued). "We found that many cytokines messenger RNAs (mRNAs), including Il1b, Il5, Il6, Il10, Il12a/Il12p70, Ifng, Ccl4, Ccl5, Tnfa, Gcsf, Cxcl1, Il1a, and Il3, were significantly induced upon B.1.351 infection in the lungs of hACE2 transgenic, BALB/c, and C57BL/6 mice." (PMID 34907154, 2021). "IL-5 levels were elevated at pretreatment showing infection." (PMID 34239575, 2021). "PFO is speculated to induce intravascular hemolysis and the production of proinflammatory cytokines, such as TNF-α, IL-5, IL-6, and IL-8 beginning in the early stage of infection in hosts infected with C. perfringens." (PMID 34385995, 2021). "The increased eosinophil recruitment previously observed may be influenced by this finding, as IL-5 enhances the differentiation and proliferation of eosinophil progenitors in the bone marrow and their migration to the infection site." (PMID 34310619, 2021). "The increase in IL-5 gene expression by eosinophils could contribute to the antiviral state of the large intestine, thereby preventing infection." (PMID 34265022, 2021). "It is therefore possible that longer-term primary infections might resolve the relative roles of IL-4Rα, IL-5, and CCR3 in eosinophil-mediated control of circulating mf." (PMID 32571840, 2020). "As the infection progresses, the immune response, modulated in part by IL-10, shifts to a mixed Th1/Th2 profile and then to a Th2 profile by 6 dpi with a significant increase of IL-4, IL-5 and IL-13 levels." (PMID 33023672, 2020). "Mice lacking ILC2s due to conditional deficiency of the transcription factor RAR-related orphan receptor alpha (Rora) displayed a massive downregulation of features of type 2 immunity as reflected by reduced levels of the type 2 signature cytokines IL-4, IL-5, and IL-13 at 14 days post-infection." (PMID 32117319, 2020). "However, the expression of IL-4 and IL-5 is increased due to infection in the taiep groups (p < 0.05)." (PMID 32817660, 2020). "In a recent report, Th2 immune responses, including IL-5 and recruited activated eosinophils, induced by infection with the intestinal helminth parasite, H. polygyrus, has been shown to promote host protective response to the lung migratory parasite, Nippostrongylus brasiliensis." (PMID 31673002, 2019). "Furthermore, the absence of NK cells resulted in reduced B. pertussis-specific IFNγ secretion and an increase in IL-5 secretion by spleen cells isolated 14 days after infection." (PMID 31507615, 2019). "The significant increase in IL4 and IL5 from single to dual infection could explain the significant decrease in parasite body length in the later group of hosts." (PMID 31871660, 2019). "Following influenza A virus infection of mice, type 2 innate lymphoid cells are recruited to the respiratory tract and produce large quantities of IL-5, which contributes to the recruitment of eosinophils into the infected lungs during the recovery phase of infection." (PMID 31415658, 2019). "However, while a role for IL-5 supporting recovery from infection was demonstrable, infection of PHIL mice, which are selectively deficient in eosinophils, surprisingly demonstrated that the recovery process in this model was independent of eosinophils." (PMID 31415658, 2019). "Additionally, T. canis-infection led to a prominent increase of anti-inflammatory IL-4 and IL-5 in the acute/subacute phase of infection which reached homeostatic levels with beginning of the chronic phase (day 42 pi)." (PMID 31315623, 2019). "Furthermore, the high percentage of ILC2s that produce IL-5 during early infection suggests that these cells are an important source of this crucial cytokine and potentiate Th2 responses to L. sigmodontis that arise later during the infection." (PMID 31072011, 2019). "The infection induces acute peritoneal recruitment of neutrophils and other innate immune cells, and the local and systemic production of proinflammatory cytokines and chemokines (IL-1β, IL-5, IL-6, TNF-α, RANTES, MIP-1β, MCP-1, KC and IL-10)." (PMID 31024025, 2019).
infection (continued). "Interestingly, a prominent peak pattern of IL-4 and IL-5 was noted in cerebra of T. canis-infected mice in the acute and subacute phase of infection." (PMID 31315623, 2019). "Results showed that the percentages of IL-4-, IL-5-, and IL-17-producing cells in TLR3+ NK cells population significantly increased after infection (IL-4: 14.73 ± 1.968% versus 8.787.97581%; IL-5: 0.03333 ± 0.03333% versus 0.9833 ± 0.1922%; IL-17: 24.50 ± 2.466% versus 51.76 ± 2.258%, P < 0.05)." (PMID 30246036, 2018). "Thus, further infection experiments should be performed in IL-17A-deficient BALB/c mice to elucidate the role and interaction of IL-5 and IL-17A." (PMID 29931394, 2018). "However, following infection, we observed significantly elevated levels of IL-1β, IL-2, IL-3, IL-5, IL-6, IL-10, IL-17A, MIP-1α, MIP-1β, KC, transforming growth factor β (TGF-β), G-CSF, and GM-CSF in HO-1−/− mice compared to HO-1+/+." (PMID 30428359, 2018). "In addition, eosinophil influx in infection, a response highly dependent on IL-5, was also reduced following anti-Ym1 treatment." (PMID 30500858, 2018). "Importantly, stimulation of harvested MLN cells with 20μg/ml α-CD3 revealed that production of Th2 cytokines (IL-4, IL-5, IL-13 and IL- 10) peaked from day 6 to day 7 post-infection and diminished at day 9 and 12 post-infection." (PMID 28651009, 2017). "On multivariable analysis, only IL5 in response to mitogen stimulation was predictive of infection." (PMID 29051761, 2017). "We identified IL-5 in response to PMA antigen stimulation as a key immune profile and defined optimal values for this profile, to assist with predicting risk of subsequent onset of infection." (PMID 29051761, 2017). "The results showed that the expressions of TNF-α, IL-12, IL-5, IL-10 and GM-CSF in serum increased from five weeks post-infection and to peak levels at week 6 post-infection; however, as typical type 1 cytokines, the levels of IL-2 and IFN-γ in serum did not change during the key period." (PMID 28539607, 2017). "Anti‐inflammatory cytokine IL‐5 decreased after CMV lytic infection." (PMID 29226079, 2017). "Indeed, in a human patient with vascular pythiosis, high levels of IL-4 and IL-5 cytokines have been detected during infection." (PMID 28542438, 2017). "Levels of nasosorption IL-13 against IL-5 (Z-score normalised) on day 0 were plotted as a 2D cluster, and demonstrate that there is reasonable discrimination between asthmatics (red dots) and healthy volunteers (blue dots) at baseline before infection." (PMID 28373098, 2017). "Infection with helminths has a profound effect on the immune system resulting in polarization towards Th2, characterized by high levels of cytokines such as interleukin-4 (IL-4), IL-5, IL-13 and high serum levels of immunoglobulin E." (PMID 26852392, 2016). "The pattern of the major cytokines associated to infection was similar in BALF, although in serum of PSGL-1−/− mice there were significant increased levels of IL-5, IL-6, and IFN-γ (P <0.05) which is compatible with the higher bacterial levels found in the blood of these mice." (PMID 26975045, 2016). "In a similar fashion, although defective Th2 immunity was observed during acute Trichuris muris infection, Icos−/− mice produced more IL-13 and IL-5 at day 35 post-infection compared with wild-type mice, suggesting that Th2 immunity was slower to develop in the absence of ICOS." (PMID 27559335, 2016). "IL-19, IL-10, IL-6, IL-27 and IL-5 also increased during late infection days." (PMID 26070790, 2015). "Additionally, PPD-specific Th2 cytokines (IL-5 and IL-10) were consistently induced after Mtb K infection compared to Mtb H37Ra and H37Rv infection." (PMID 26675186, 2015). "In accordance with the elevated numbers of neutrophils and eosinophils in the peripheral blood and histological sections, we detected prominent increases in TH2 cytokines, such as IL-4, IL-5, IL-13 and IL-33, during the acute phase of infection, particularly from the 3rd day p.i. onward." (PMID 26135397, 2015).